CD4 (CD4 molecule)
Diseases named in the same sentence as CD4 in open-access papers (continued):
Sharing a sentence is not in itself a finding about the gene and the disease.
COVID-19 (continued). "In most cases, lymphopenia with decreased absolute counts of CD4+ and CD8+ T cells, B cells, and natural killers (NK) cells have been detected in patients with COVID-19, excluding mild forms." (PMID 34696395, 2021). "Conversely, in COVID-19 patients with aTB, SARS-CoV-2 responses were only detected in 40% of participants, whereas 14/15 (93%) exhibited an M. tuberculosis–specific CD4 response." (PMID 33945513, 2021). "The quality and breadth of CD4+ and CD8+ T cell response plays a key role in COVID-19 resolution and modulation of disease severity." (PMID 34943875, 2021). "The mean values of CD3+CD4+, CD16+CD56+, CD4/CD8 ratio, CD3+CD4+%, and CD16+CD56+% in COVID-19 patients were significantly higher than those in patients with CAP." (PMID 34150910, 2021). "In our study, we observed S-specific CD4+ and CD8+ T cell responses in 50% and 15% of the recovered Chinese COVID-19 patients, respectively." (PMID 33563974, 2021). "In summary, these data suggest that hospitalized COVID-19 patients show a T cell signature typified by an accumulation of activated CD8+ and CD4+ T cells and CD4+ PD-1+ T cells." (PMID 34745145, 2021). "As reported by Chen and coworkers, the number of CD4+ and CD8+ T cells was markedly lower in severe cases of COVID-19 than in moderate cases." (PMID 33936104, 2021). "NEAT1 was overexpressed in nine cell types identified from severe COVID-19 patient BAL samples, including in M1 and M2-type macrophages, monocytes, CD4+ T cells, and CD8+ memory T cells." (PMID 34564316, 2021). "CD4 and CD8 T cells are present and can be directly detected in the blood of convalescent COVID-19 patients even up to 6 to 8–9 months post infection, irrespective of their disease severity." (PMID 34471260, 2021). "In the pooled COVID-19 patients, ACE2 was expressed in several immune cells, such as dendritic cells, CD14 monocytes, CD4 memory T cells, CD4 naive T cells, CD8 effector T cells, etc.; TMPRSS2 was expressed in most immune cells." (PMID 34578338, 2021). "Limited data suggest that SARS-CoV-2-specific CD4+/CD8+ T cells can persist for up to 3–5 months and IgG to the spike protein up to eight months in COVID-19 patients." (PMID 33807247, 2021). "Reduced numbers of both CD4+ and CD8+ T cells in blood samples are consistently observed in patients suffering COVID-19, particularly in more severe cases." (PMID 33810287, 2021). "Among the COVID-19 patients, SARS-CoV-2 S-reactive CD4+ T cells were identified in 15 out of 18 patients (83%)." (PMID 33672450, 2021). "We performed a comprehensive flow cytometry analysis of SARS-CoV-2–specific CD4+ and CD8+ T cells from COVID-19–naive and –recovered donors before and after mRNA vaccination." (PMID 34035118, 2021). "Lymphopenia with a significantly lower number of CD4+ T cells and a higher number of CD8+ T cells was described in severe COVID-19 cases, which correlated with mortality." (PMID 34578460, 2021). "First, it was proved that CD3+T, CD4+T, CD8+T cells and NK cells were markedly reduced among COVID-19 patients." (PMID 34766001, 2021). "In some studies, immunosuppression was described as a consequence of a drastic reduction in the number of both CD4+ and CD8+ T cells in moderate and severe COVID-19 patients." (PMID 34414199, 2021). "In COVID-19 patients, Th17 cells (CD3+CD4+) have been described as increased and participating in the cytokine storm." (PMID 34436366, 2021). "The levels of effector CD4+ T cell subpopulations TEM and TEMRA were increased 1.5-fold in patients with severe and critical COVID-19, in comparison with mild COVID-19." (PMID 34122423, 2021). "In convalescent COVID-19 patients, we found significant enrichment in the CD45RA- (memory) compartment of the CD4+ T cells with stimulation." (PMID 34113347, 2021). "Memory CD4+ T cells and CD8+ T cells were detected in 100% and 70% in patients who have recovered from COVID-19, respectively, with high titers of immunoglobulin G (IgG) antibodies which herald further protective immunity." (PMID 33613576, 2021).
COVID-19 (continued). "In both OTD-CoV-2pos and severe COVID-19 patients, significant correlations were observed between MP_R and MP_S induced AIM expression (CD134 and CD137) in CD4+ T cells." (PMID 34858405, 2021). "There have been interesting observations on virus-specific CD4+ and CD8+ T cells in sera from both patients with acute COVID-19 and convalescent patients." (PMID 34780495, 2021). "Next, we measured the sizes of virus-specific memory pools for CD4+ and CD8+ T cells from 89 COVID-19 patients (1 COVID-19 sample was used up), 69 close contacts and 30 healthy donors by using an overnight “ex vivo” peptide stimulation assay." (PMID 33741972, 2021). "Peripheral counts of CD4 and CD8-T cells are similarly low in patients with COVID-19, which is demonstrated as lymphopenia, a surrogate marker of severe COVID-19, albeit with a higher ratio of pro-inflammatory Th17 cells." (PMID 33320454, 2021). "More important, the TRBV6-5-TRBD2-TRBJ2-7 combination with high frequency was shared between CD4+ T and CD8+ T cells of different COVID-19 patients." (PMID 35011632, 2021). "On the contrary, with decreasing peripheral CD3+CD4+ or CD3+CD8+ T cells 6-9 days after baseline, COVID-19 exacerbation quickly occurred within 1 or 2 weeks of admission." (PMID 33741750, 2021). "In the mild group (71 CAP and 257 COVID-19), COVID-19 patients showed decreased CD19+, CD3+CD8+%, and increased CD3+CD4+%, compared with that of CAP patients." (PMID 34150910, 2021). "In the presence of adequate neutralizing antibodies, CD4+ and CD8+ T cells play a major role in the recovery of critical COVID-19 patients." (PMID 33741972, 2021). "The counts of lymphocyte subpopulations (CD3+ T cells, CD4+ T cells, CD8+ T cells, B cells and NK cells) were reported to decline in the peripheral blood of patients with COVID-19." (PMID 34123873, 2021). "SARS-CoV-2 specific CD4+T cells and CD8+T cells have been identified in the recovered COVID-19 patients and these are shown to recognize peptides of viral spike, nucleoprotein, and matrix as well as other viral proteins." (PMID 33632295, 2021). "As in the CD4 compartment, a smaller fraction of CD8+ T cells from COVID-19 patients expressed α4β7 integrin (as indicated by positive staining for vedolizumab) compared to healthy controls." (PMID 33959123, 2021). "Kidney transplant recipients with COVID-19 present less fever as an initial symptom, lower CD3, CD4, and CD8 cell counts, and more rapid clinical progression than patients with COVID-19 in the general population." (PMID 34063052, 2021). "COVID-19 patients displayed an immune phenotype characterized by increased HLA-DR+CD38+ and PD-1+ CD4+ and CD8+ T cells, and elevated CD8+CD244+ lymphocytes, compared to healthy controls." (PMID 33717195, 2021). "The report demonstrated the presence of virus specific CD4+ cells in 100% and CD8+ cells in 70% of recovered COVID-19 patients." (PMID 34276652, 2021). "Dissecting further, HLA-DR+CD4+ cells were downregulated, while HLA-DR+CD8+ were upregulated, in COVID-19 patients compared to HCs." (PMID 33808906, 2021). "In the current study, we assessed immune memory of all three branches of adaptive immunity (CD4+ T cell, CD8+ T cell, and humoral immunity) in a predominantly cross-sectional study of 188 recovered COVID-19 cases, extending up to eight months post-infection." (PMID 33408181, 2021). "Balanced activation of acquired SARS-CoV-2 specific immune responses, which include CD4+ and CD8+ T cells with a memory phenotype and neutralizing antibody responses, is required for host protection in acute COVID-19." (PMID 34663207, 2021). "Severe COVID-19 patients, besides the age, show a reduction in CD4+ and CD8+ lymphocytes absolute number, while T cells subsets and CD4+/CD8+ ratio remain stable." (PMID 34201847, 2021). "We then evaluated the ability of CD4+ and CD8+ T cells from the COVID-19 convalescent HCW cohort to proliferate in response to peptide pools spanning key proteins from SARS-CoV-2." (PMID 33824342, 2021).
COVID-19 (continued). "Lymphopenia, characterized by a reduction in peripheral CD4 and CD8 T-cells, is also a prominent feature of severe COVID-19." (PMID 33557908, 2021). "Previous studies suggested that CD4+T and CD8+T cell levels were reduced in the vast majority of patients with severe or moderate COVID-19." (PMID 33435865, 2021). "Several reports have shown that moderate to severe COVID-19 patients with lymphopenia drastically reduce CD8 T cell and CD4 T cells in peripheral blood." (PMID 33716737, 2021). "Both SARS-CoV-2 specific CD4 + and CD8 + T cells, as well as B cells against SARS-CoV-2 epitopes, have been found for up to 6 months after infection in about 95% of COVID-19 patients." (PMID 33936045, 2021). "A reduction of peripheral lymphocyte counts, including CD4+ and CD8 + T cells, B cells and NK cells, has been observed in COVID-19 patients." (PMID 34251989, 2021). "In a study of 36 individuals recovering from mild to severe COVID-19, all had SARS-CoV-2–specific CD4+ and CD8+ T cells that recognized multiple regions of the SARS-CoV-2 nucleocapsid (N) protein." (PMID 33815415, 2021). "The data discussed here extend these observations, showing that the CD3+CD4+ and CD16+CD56+ lymphocyte counts were higher but the TNF-α and IFN-γ were lower in COVID-19 patients compared with those of CAP patients." (PMID 34150910, 2021). "CD4 and CD8 T lymphocytes originating from COVID-19 patients released significantly less IL-2, TNFA and IFN-γ upon T-cell engagement or polyclonal stimulation." (PMID 33420356, 2021). "A successful T cell response was doubted initially because of the observed lymphopenia with reduced CD4+ and CD8+ T cell numbers in severe COVID-19 cases." (PMID 33608656, 2021). "In our study, we observed N-specific CD4+ and CD8+ T cell responses in 65% and 50%, respectively, of recovered Chinese COVID-19 patients, respectively." (PMID 33563974, 2021). "In this study, all patients were on stable cART with undetectable HIV viral load, and most subjects had CD4 + T cell count above 200 cells/mm3, as much as observed in another case series of 27 HIV-positive persons with COVID-19 in New Jersey." (PMID 32748333, 2021). "Higher levels of activated CD4 and CD8 T cells were described in COVID-19 pediatric patients with MIS-C." (PMID 34659235, 2021). "Compared with respiratory cancer patients, COVID-19 patients had lower levels of IL-2 and higher levels of CD3+CD4+ T cells and CD19+ B cells." (PMID 34712741, 2021). "The difference in tp CD4+ NCAP reactive T cells was even more prominent, when we pooled the data of this study with HCs and post COVID-19 Ab+ of our already published cohort." (PMID 34322120, 2021). "The presence of SARS-CoV-2-reactive CD4+ and CD8+ T cells was also found in acute patients with COVID-19 admitted to ICU at similar frequencies." (PMID 35004764, 2021). "Studies have reported that the number of total T cells, and CD4+ and CD8+ T cells, were dramatically reduced in COVID-19 patients, especially in patients requiring ICU care, and this was negatively correlated with patient survival." (PMID 33640878, 2021). "Mild COVID-19 patients exhibit more CD8+ CTL cells, while patients with severe disease have predominantly increased SARS-CoV-2-specific CD4+ T cells in their recovery-stage of the disease." (PMID 33808998, 2021). "Negative correlations were observed between the frequencies of MDSCs and the absolute count of CD3+, CD3+CD4+, and CD3+CD8+ T cells, and CD3-CD16+CD56+ NK cells in COVID-19 patients." (PMID 33640878, 2021). "T cell reactivity in response to S peptide pools of HCoVs were variable with slightly lower frequencies of CD4+CD154+CD137+ activated T cells reactive to C-terminal S of HCoV-229E and -OC43 in post COVID-19 individuals compared to HC." (PMID 34322120, 2021).
COVID-19 (continued). "In one clinical study, high activity of caspase-1 was detected in CD3+ CD4+ CD45+ T cells and CD3+ CD45+ T cells, and increased levels of lactate dehydrogenase, a marker of pyroptosis, and IL-18 were observed in COVID-19 patients." (PMID 34360684, 2021). "Reports have demonstrated that the frequency of CD4+ and CD8+ T cells is reduced in COVID-19 patients." (PMID 33596401, 2021). "Another study investigated virus-specific CD4+ and CD8+ T cells of 10 COVID-19 patients with severe ARDS." (PMID 34194438, 2021). "We observed a statistically lower percentage of CD4+ CD25+ and CD8+ CD25+ cells in the COVID-19(+) group compared to boththe HC and COVID-19(−) virus group." (PMID 33419040, 2021). "Although the literature is still emerging, in general, studies have observed that COVID-19 patients with controlled HIV coinfection and preserved CD4+ T cell counts have similar clinical trajectories to those without HIV infection." (PMID 34252054, 2021). "Compared to COVID-19 patients with normal FT3 serum values, patients with low FT3 serum values show reduced CD4+ and CD8+ T lymphocytes at CyTOF analysis and these results are in agreement with those observed at FCA." (PMID 33794925, 2021). "Consistent with viral infection triggering immune response, the frequencies of cycling immune cells, and cycling CD4+ and CD8+ T cells were increased among COVID-19 patients compared to controls." (PMID 35095917, 2021). "In the COVID-19(+) group there was a significantly positive correlation between the percentage of RE-LYMP and CD4+ CD38+ lymphocytes (R = 0.5, p < 0.05) and between the percentage of RE-LYMP and GMF CD8+ CD45RO intensity (R = 0.7, p < 0.05)." (PMID 33419040, 2021). "Our ex vivo stimulation analyses demonstrated that the pool sizes and quality of the SARS-CoV-2-specific CD4+ and CD8+ T memory cells from close contacts were around half of those from COVID-19 patients." (PMID 33741972, 2021). "Here, we determined the level of CD4+ and CD8+ memory T-cell responses in COVID-19 convalescents by stimulating PBMCs collected 1 to 6 months after recovery with sucrose gradient-purified live SARS-CoV-2." (PMID 34452355, 2021). "Reported CD4 + T lymphocyte count and HIV RNA value were the last measurements before the COVID-19 diagnosis." (PMID 32748333, 2021). "In conclusion, we presented a dominant epitope of SARS-CoV-2 S from the PBMCs of COVID-19 convalescent patients, represented by the peptide B65, together with its specific functional TCR for CD4+ T cells." (PMID 34805136, 2021). "The numbers of both CD4+ T cells and CD8+ T cells in patients with COVID-19 were lower than those in healthy donors, and the decrease in Th cells was more pronounced in severe cases." (PMID 33923792, 2021). "Compared to that in HDs, there is a significant increase COVID-19 patient in the proportion of memory CD8+ T cells (TCs and Covs), while memory CD4+ T cells were mildly elevated in TCs and Covs although there was no statistical difference." (PMID 34862879, 2021). "In patients with COVID-19, the level of Treg cells (CD3+CD4+CD25+ CD127low+) decreases, the level of Th17 cells (CCR6+ Th17) increases, and the ratio of Treg/Th17 cells decreases." (PMID 34458162, 2021). "Our findings demonstrated that lymphocyte subsets features, especially CD16+CD56+%, CD4+/CD8+ ratio, CD19+, and CD3+CD4+ independently predicted the differentiation of COVID-19 and CAP." (PMID 34150910, 2021). "Conversely, in non–COVID-19 controls, most SARS-CoV-2–reactive CD4+ T cells were distributed between triple functional cells (IL-2+IFN-γ+TNF-α+) and cells coproducing IFN-γ and TNF-α." (PMID 33945513, 2021). "Persistent changes including subset distribution, cell division, and expression of activation/exhaustion of circulating CD4+ T and CD8+ T cells were observed in recovered COVID-19 patients compared with healthy controls for at least six months." (PMID 33995364, 2021).
COVID-19 (continued). "It is the key element for mediating viral entry as well as a crucial antigenic determinant capable of stimulating protective immune response through elicitation of anti-SARS-CoV-2 antibodies and activation of CD4+ and CD8+ cells in COVID-19 patients." (PMID 33672450, 2021). "A study found that CD4 + T cells and CD8 + T cells were significantly reduced by in patients with COVID-19 in ICU in Wuhan." (PMID 34074305, 2021). "Recent studies have also reported decreased lymphocytes, particularly CD4+ and CD8+ T cells, in the peripheral blood of COVID-19 patients were in correlation with disease severity." (PMID 33461503, 2021). "In the COVID-19(+) there was a lower proportion of CD4+ CD38+ cells than in the other groups (significant differences between COVID-19(+) and COVID-19(−) virus groups)." (PMID 33419040, 2021). "This is also supported by our own data showing increased TIM-3 expression on CD4+ and CD8+ T cells of patients with severe and fatal COVID-19." (PMID 34858405, 2021). "Higher levels of interleukin IL-6 and IL-10, and lower levels of CD4+T and CD8+T are also observed in patients with COVID-19 and these correlate with the severity of disease." (PMID 33643932, 2021). "Depletion of both CD4+ and CD8+ T cells has been reported in COVID-19 patients, in addition to phenotypic alterations in specific T cell subsets, which have recently been extensively reviewed by our consortium." (PMID 35593707, 2021). "Regarding the general cell response, we present the following findings: autopsies of patients with COVID-19 revealed increased cell exhaustion and SARS-CoV-2 CD4+ expressing IFN-γ, TNF-alpha, and IL-2 indicating a Th1 cellular response." (PMID 34571855, 2021). "Another much more recent study found a high frequency of central memory CD4 + CCR6 + Th17 subpopulations and high circulating IL-17 levels in the critically ill patients with COVID-19." (PMID 34064728, 2021). "Stimulation of CD4+ T lymphocytes with protein M or N of SARS-CoV-2 revealed no significant changes in cell activation between patients with mild, severe or critical COVID-19." (PMID 34194438, 2021). "The lung tissue of our COVID-19 cohort harbored a similar frequency of CD3 T cells as the non-COVID-19-DAD control group, with the majority of T cells expressing CD4 in both cohorts." (PMID 34441292, 2021). "In agreement with findings from patients with COVID-19, IFN-γ+CD4+ T cells dominated over IFN-γ+CD8+ T cells after SARS-CoV-2 Moderna mRNA-1273 immunization." (PMID 35004764, 2021). "In these 395 COVID-19 patients, Hs-CRP (5.0 [2.2–22.9] mg/L) and PCT (0.05 [0.03–0.08] ng/ml) levels were elevated, while lymphocytes, CD4+T and CD8+T cell levels were all within the standard ranges." (PMID 33435865, 2021). "Pulmonary infiltrating CD4 T cells with cytotoxic capacity, as measured by Granzyme B, identified in our PTM and recently in humans with severe COVID-19, are a unique and possibly understudied aspect of the disease." (PMID 34929014, 2021). "Although there is a decrease in CD4 and CD8 lymphocyte cells and NK cells in the most severe cases of COVID-19, hyperactive circulating monocytes continue to produce proinflammatory cytokines, such as TNFα and IL-6." (PMID 33791232, 2021). "In moderate cases of COVID-19, CD8+ T cells were markedly expanded with higher levels of effector molecules, e.g., XCL1, and a naïve phenotype for CD4+ T cells in severe cases." (PMID 34527720, 2021). "In the COVID-19 BAL samples, CD4+ T cells overexpressed MALAT1 in mild patients and under-expressed it in severe cases." (PMID 34564316, 2021). "It is reported that a whole decline of lymphocyte subsets including CD4+ and CD8+ T cells, B cells, and NK cells were presented in severe and deceased COVID-19 patients." (PMID 34210280, 2021). "The PBMCs from MSC-treated COVID-19 patients contained higher proportions of CD16+ monocytes and lower proportions of CD4+ T and B cells than the placebo group." (PMID 34702946, 2021).